MFN2 (mitofusin 2)
Diseases named in the same sentence as MFN2 in open-access papers (continued):
Sharing a sentence is not in itself a finding about the gene and the disease.
myocardial infarction (20 papers, 2016 to 2023). Gross necrosis of the myocardium, as a result of interruption of the blood supply to the area, as in coronary thrombosis. "In summary, despite apparent mitochondrial dysfunction, hearts deficient in both Mfn1 and Mfn2 are protected against acute myocardial infarction due to impaired mitochondria/SR tethering." (PMID 27228353, 2016). "Thereafter, the SVM-RFE algorithm, random forest algorithm, and LASSO algorithm were utilized to identify mitophagy genes associated with myocardial infarction, including ATG5, TOMM20, and MFN2." (PMID 37304955, 2023). "In this line, it has been demonstrated that moderated interval training resulted in improved mitochondrial fusion and fission in male rats with myocardial infarction increasing Mfn2 and PGC-1α and reducing Drp1." (PMID 37955687, 2023). "In the rat hearts followed for 12 to 18 weeks after myocardial infarction, Mfn2 was reduced, and Fis1 was increased, but Opa1 expression was unchanged." (PMID 37895224, 2023). "It was shown that acute ablation of both cardiac Mfn1 and Mfn2 makes the heart resistant to acute myocardial infarction." (PMID 35890161, 2022). "Downregulation of Mfn2 was noted in cardiac hypertrophic models including spontaneous hypertension, myocardial infarction (MI) and transverse aortic banding, all of which led to unfavorable myocardial remodeling." (PMID 35624099, 2022). "Acute knockout of Mfn1 and Mfn2 in the heart showed a short-term protective effect against acute myocardial infarction, related to the decreased contact between mitochondria and endoplasmic reticulum, thereby reducing the calcium overload in the mitochondria." (PMID 34660720, 2021). "In summary, we have shown that acute ablation of both cardiac Mfn1 and Mfn2 rendered the heart resistant to acute myocardial infarction." (PMID 27228353, 2016). "We found that the acute ablation of both cardiac Mfn1 and Mfn2 protected the heart against acute myocardial infarction." (PMID 27228353, 2016). "Additionally, melatonin has been shown to increase MFN2 response and prevent myocardial infarction injury." (PMID 38001815, 2023). "Additionally, heart-specific Mfn1/Mfn2 double KO Mice exhibit a smaller myocardial infarction size in response to I/R." (PMID 37895224, 2023). "Furthermore, Evans-TTC staining showed that rAAv-MFN2 rescued the myocardial infarction size in diabetic MI/R mice compared to that in the MI/R group mice." (PMID 37537600, 2023). "Interestingly, another study reported the opposite observation, they showed that ablation of MFN1 and MFN2 genes had a protective effect on myocardial infarction, and the mechanism was related to inhibition of MPTP opening, reduction of oxidative stress, and attenuating mitochondrial Ca2+ overload." (PMID 35783853, 2022). "MFN2 is also downregulated in rat models of myocardial infarction (MI), transverse aortic banding and spontaneously hypertensive rats." (PMID 36187489, 2022). "Compared with WT mice, myocardial infarct size was reduced by 46%, and MAM formation and ROS generation were reduced in MFN2 ablation mice in the IRI model." (PMID 36588561, 2022). "Post-myocardial infarction rat models also exhibit the reduced mitochondrial fusion, which is relevant to ERK1/2 and JNK activation and the reduced OPA1 and MFN2 expressions." (PMID 31118889, 2019). "Similarly, rat hearts followed for twelve to eighteen weeks after myocardial infarction exhibited a decrease in MFN2, an increase in Fis1, and no change in OPA1 expression." (PMID 28190190, 2017).
atherosclerosis (19 papers, 2013 to 2026). A disease characterized by the build-up of fatty material and calcium deposition in the arterial wall resulting in partial or complete occlusion of the arterial lumen. "The role of Mfn2 in atherosclerosis progression can also be associated with the increase in expression of the cellular carrier of cholesterol in macrophages by activation of PPAR-γ and inhibition of several elements of the MAPK/ERK routes." (PMID 39940788, 2025). "Morphologic analysis also demonstrated that MFN-2 overexpression inhibited atherosclerosis formation by 66% and reduced intima/media thickness by 74.6%." (PMID 39861173, 2025). "A fish oil-rich diet can improve endothelium-dependent vascular relaxation and delay the progression of atherosclerosis by upregulating the expression of MFN2 and OPA1 in aortas of ApoE−/− mice fed with high-fat diet." (PMID 40093324, 2025). "For example, in a rabbit model of atherosclerosis, MFN-2 overexpression inhibited the formation of oxidized-LDL and VSMC migration." (PMID 39861173, 2025). "Mfn2 expression is reduced in atherosclerosis models, and conversely, Mfn2 overexpression reduces atherosclerotic lesions in rabbits." (PMID 36860274, 2023). "In spontaneously hypertensive or atherosclerosis-prone rats, Mfn-2 levels were diminished in VSMCs, while Mfn2 overexpression inhibited the proliferation of VSMCs and sensitized them to H2O2-induced apoptosis." (PMID 36439260, 2022). "Another study has suggested that overexpression of MFN2 can reduce plaque formation and endothelial cell injury in rabbit models of atherosclerosis." (PMID 36588561, 2022). "Reduced plaque progression and decreased VSMC proliferation were observed in a rabbit model of atherosclerosis in response to the overproduction of Mfn2, which represent the anti-atherogenic properties of human Mfn2." (PMID 33669743, 2021). "Human MFN2 exerts antiatherogenic properties in a rabbit model of atherosclerosis, while MFN2 overproduction leads to reduced VSMC proliferation/hyperplasia and diminished plaque progression." (PMID 34336092, 2021). "Reduced Mfn2 levels are observed in spontaneously hypertensive or atherosclerosis‐prone rat VSMCs, whereas Mfn2 overexpression decreases VSMC proliferation and sensitizes cells to H2O2‐induced apoptosis." (PMID 29068134, 2018). "Mfn2 expression is diminished in highly proliferative VSMCs from atherosclerosis‐prone or balloon‐injured rats, and Mfn2 overexpression blocks proliferation of neointimal VSMCs after balloon injury." (PMID 29068134, 2018). "While expression of Mfn2 has increased in wild-type macrophages as well as brain and cardiac cells, in ApoE-/- mice, the expression of Mfn2 was significantly reduced during atherosclerosis progression." (PMID 39940788, 2025). "These processes are controlled by mitochondria-associated small GTPases, including the mitochondria 2 fusion protein (mitofusin 2, Mfn2), which reduces proliferation and promotes apoptosis of smooth muscle cells, which makes this protein a potential target for the treatment of atherosclerosis." (PMID 34017868, 2021). "The decreased expression of MFN1 and MFN2 promotes atherosclerosis in animal models." (PMID 34938787, 2021). "Recent studies have demonstrated that MFN2 acts as an endogenous Ras inhibitor and that deregulation of MFN2 expression leads to vascular proliferative disorders in the settings of genetic hypertension, atherosclerosis, and restenosis after vascular injury." (PMID 24174980, 2013). "It has been well-documented that overexpression of MFN2 inhibits the secretion of inflammatory factors in RAW 264.7 macrophage cells and attenuates atherosclerosis progression." (PMID 36588561, 2022). "In macrophage-enriched murine atherosclerosis lesion areas, the level of dynamin-related protein-1 (DRP1) is downregulated and MFN2 is upregulated as the lesion progresses." (PMID 34938787, 2021).
atherosclerosis (continued). "Furthermore, to investigate the involvement of MAMs in atherosclerosis pathogenesis, we examined the expression of three core MAMs-related molecules—Mitofusin 1 (MFN1), Mitofusin 2 (MFN2), and Mitochondrial Fission 1 (Fis1)—in the same PBMC samples." (PMID 41614904, 2026). "The mitochondrial fusion proteins MFN1 and MFN2 maintain the mitochondrial network and protect endothelial cell function by initiating OMM fusion.Reduced expression of MFN1 and MFN2 leads to endothelial dysfunction and inhibition of VSMC proliferation, promoting the progression of atherosclerosis." (PMID 40093324, 2025).
melanoma (19 papers, 2016 to 2025). A malignant, usually aggressive tumor composed of atypical, neoplastic melanocytes. "Another study revealed that the parkin expression was increased in melanoma, while parkin deficiency induced apoptosis and suppressed the growth of melanoma tumors through the inhibition of mitofusin-2 (Mfn2) ubiquitination." (PMID 40943612, 2025). "For example, in melanoma, Parkin deficiency can induce apoptosis and inhibit melanoma development and metastasis by inhibiting Mfn2 ubiquitination." (PMID 36200262, 2022). "During periods of oxidative stress, astrocytes transfer intact mitochondria to melanoma cells, and this occurs through the action of Miro1 and Mitofusin-2." (PMID 41463339, 2025). "In a previous report we showed that senescence, induced by the DNA methylating agent temozolomide, increased the level of fusion proteins mitofusin 1 and 2 in melanoma, and silencing Mfn1 or Mfn2 expression reduced interleukin-6 secretion by senescent cells." (PMID 38195762, 2024). "As seen in an in vitro model, melanoma cells degrade MFN2 to achieve ER stress resistance: the mechanism for this degradation relies solely on MARCH5, as only the silencing of this ligase was able to restore the protein levels of MFN2 in melanoma." (PMID 38139010, 2023). "ER stress resistance can be induced by dysregulating mitophagy, inducing mitochondrial fission and inhibiting the expression of MFN2, thus making melanoma cells insensitive to this kind of therapy." (PMID 38139010, 2023). "MFN2-silencing elevates mitochondrial ROS levels that in turn increased melanogenesis in a B16 mouse melanoma cell line-based low-density culturing-induced pigmentation model." (PMID 35453623, 2022). "Here, using a B16 mouse melanoma cell line and primary human melanocytes, we report that MFN2 negatively regulates melanogenesis." (PMID 35203350, 2022). "In cutaneous melanoma both FIS1 and MFN2 protein expression correlated with a higher Clark level—a staging measure of how deep melanoma has invaded in the skin." (PMID 35356277, 2022). "Recently, MARCH5 was reported to trigger mitochondrial fission and mitophagy in response to ER stress by facilitating the ubiquitination and degradation of MFN2 in melanoma." (PMID 36192752, 2022). "We found that the levels of Mfn1 and Mfn2 and Opa1 protein were considerably reduced in cryptolepine treated melanoma cells." (PMID 28473727, 2017). "The results showed that knockout of MFN2 in the B16F10 melanoma cells significantly promoted metastasis in lung tissue at 14 days after injection, suggesting that MFN2 inhibits tumor migration and invasion in vivo." (PMID 28176801, 2017). "Additionally, NDUFS3 overexpression in melanoma cells leads to increased Mfn2 and decreased DRP1, with the opposite effects observed upon NDUFS3 knockdown." (PMID 40404919, 2025). "This molecular axis between XBP1, MARCH5 and MFN2 could be targeted to use ER stress to reduce cancer progression in melanoma." (PMID 38139010, 2023). "To further address whether MFN2 regulates the metastasis of tumor cells, we knocked out MFN2 in B16F10 melanoma cells, which showed high invasion ability in vivo." (PMID 28176801, 2017). "Moreover, Mfn2 siRNA significantly increased vemurafenib-induced cell death in vemurafenib-resistant melanoma cell lines A375RIV and SKMEL28V3, which exhibited a high OXPHOS phenotype." (PMID 27250023, 2016). "Blocking Miro1 and Mitofusin-2 halts TNT-mediated mitochondrial transfer and thus isolates melanoma metabolically." (PMID 41463339, 2025). "As such, lower levels of DDR1, MFN2 and OPA1 and higher levels of pAMPK and higher amoeboid scores were also found at the IF of human melanoma metastatic lesions." (PMID 37217519, 2023). "Accordingly, melanoma cells at the IF of human primary tumours showed lower levels of DDR1, MFN2 and OPA1, while harbouring higher levels of pAMPK and higher amoeboid score." (PMID 37217519, 2023).
melanoma (continued). "In mouse xenograft models, Mfn2 knockdown did not alter tumor volume, whereas the absence of Mfn2 significantly prolonged the anti-melanoma effect of vemurafenib." (PMID 27250023, 2016). "Further studies will need to be performed to determine mechanistically why certain melanoma subtypes may rely more on MFN2 as opposed to FIS1." (PMID 35356277, 2022).
Parkinson disease (19 papers, 2015 to 2025). A progressive degenerative disorder of the central nervous system characterized by loss of dopamine producing neurons in the substantia nigra and the presence of Lewy bodies in the substantia nigra and locus coeruleus. "Mutations in the Mfn2 gene have been linked to Charcot–Marie–Tooth syndrome, and dysregulation of Mfn2 may be linked to multiple diseases, including Alzheimer’s and Parkinson’s diseases." (PMID 36044551, 2022). "MFN2 associates with many common neuropathies including Parkinson’s disease." (PMID 33143278, 2020). "However, causative evidence for a role of MFN2-dependent mitophagy via PINK1/Parkin in Parkinson’s disease is still missing." (PMID 31156446, 2019). "Loss of Mfn2 or conditional knockout of neuronal Mfn2 in mice has recently been reported to result in age-dependent motor deficits, followed by the loss of dopaminergic terminals in the striatum, suggesting a role for Mfn2 in parkinsonism." (PMID 26340618, 2015). "The neuroprotective potential of MFN2 was previously studied in experimentally induced Parkinson’s disease." (PMID 36287214, 2022). "Consistent with the MPTP-induced neurotoxicity in motor functions, parkinsonism-related neurotoxicity of SN DA neurons and striatal terminals were also inhibited by MFN2 OE in vivo." (PMID 33435331, 2021). "Here, we identify a detailed timeline of molecular events driving the severe and progressive parkinsonism in mice with disruption of Mfn2 in the adult nigrostriatal DA system." (PMID 34570766, 2021). "Together, these results indicate that MUL1 compensates for Parkinson’s phenotypes, caused by the loss of PINK1/Parkin or VSP35, by decreasing MFN2." (PMID 31156446, 2019). "Higher levels of Mfn2 in Parkin knockout mice fibroblasts and Parkinson's disease patients were responsible for increased ER–mitochondria association." (PMID 29068134, 2018). "In dopaminergic neurons, Slc6a3-Cre-mediated deletion of floxed Mfn1 was well tolerated, whereas deletion of Mfn2 provoked mitochondrial abnormalities, neuronal death, and a Parkinson's disease-like neuromuscular phenotype." (PMID 25861797, 2015). "Moreover, liraglutide has been reported to increase Mfn2 levels in a mouse model of Parkinson’s disease." (PMID 39457518, 2024). "For Parkinson’s disease, it was shown that these proteins Mfn2, Opa1, Drp1, and Fis1, which are involved in the control of mitochondrial fusion and fission and are downregulated in a rotenone-induced Parkinson’s disease model remained at a normal level by resveratrol administration." (PMID 37232719, 2023). "Indeed, Parkinson’s-linked mutations of VPS35, a retromer component for endosomal trafficking, correlated with increased ubiquitylation and decreased levels of MFN2, dependent on the proteasome." (PMID 31156446, 2019). "Regarding Parkinson’s disease, the link originates from MFN2 being a target of Parkin." (PMID 31156446, 2019). "The Parkinson's disease‐associated proteins Parkin and PINK1 are involved in the ubiquitination of Mfn2 on damaged mitochondria, which promotes local fission of the mitochondrial network thereby segregating damaged mitochondria for autophagic clearance (Ziviani, Tao & Whitworth, 2010)." (PMID 29068134, 2018).
dilated cardiomyopathy (18 papers, 2015 to 2025). Cardiomyopathy which is characterized by dilation and contractile dysfunction of the left and right ventricles. "While these findings indicate a clear association between MFN2 and dilated cardiomyopathy, further research is needed to elucidate the underlying mechanisms fully." (PMID 40520935, 2025). "A previous study demonstrated appearance of morphologically and functionally abnormal mitochondria in MFN2-deficient mouse cardiomyocytes that caused respiratory dysfunction and dilated cardiomyopathy." (PMID 31024341, 2019). "When Drp1 is ablated in the adult mouse heart causing hyper-fused mitochondria, the mice show dilated cardiomyopathy, while ablation of both Mfn1 and Mfn2 in the adult mouse heart causes a decrease in mitochondrial fusion leading to hypertrophy of the heart." (PMID 30102730, 2018). "Genetic analyses have linked MFN2 dysfunction to dilated cardiomyopathy." (PMID 40520935, 2025). "Mutations in the gene encoding mitofusin 2 have been predominantly associated with nerve damage, but recent studies have demonstrated that interfering with the scheduled degradation of mitochondria can result in the development of dilated cardiomyopathy." (PMID 39200108, 2024). "In contrast, cardiac Mfn2 ablation causes early-dilated cardiomyopathy in mice." (PMID 34660720, 2021). "Additionally, in mouse heart, hypertrophy or dilated cardiomyopathy result from either MFN1 or MFN2 deletion (which causes mitochondrial fragmentation) or DRP1 deletion (which causes hyperfused mitochondria)." (PMID 34608863, 2021). "These are valuable findings on the link between mitofusin 2 function and Parkin-mediated mitophagy, showing that a combination of mitophagy and mitochondrial fusion defects can lead to genetic dilated cardiomyopathy." (PMID 39200108, 2024). "In previous literature, MFN2−/− mice spontaneously developed dilated cardiomyopathy with mitochondrial dysfunction and hyperfragmentation and targeting MFN2 effectively alleviated imbalanced dynamics as well as diabetic cardiomyopathy in obese diabetic mice." (PMID 36106556, 2022). "Conditional knock out of Mfn1 and Mfn2 in adult hearts induced mitochondrial fragmentation, mitochondrial respiratory dysfunction, which lead to dilated cardiomyopathy." (PMID 33049718, 2020). "Further studies have shown that the accumulation of morphologically and functionally abnormal mitochondria induces respiratory dysfunction, which leads to dilated cardiomyopathy in Mfn2-KO mouse embryonic fibroblasts and cardiomyocytes, as well as in Parkin-KO Drosophila heart tubes." (PMID 40520935, 2025). "Conditional ablation of Mfn1 and Mfn2 in the adult heart induces mitochondrial fragmentation, cardiomyocyte dysfunction, and impaired mitochondrial respiration, ultimately leading to rapidly progressive and lethal dilated cardiomyopathy." (PMID 40520935, 2025). "Interestingly, mice with cardiac MFN1 deficiency maintained cardiac function and mitochondrial respiration, while cardiac MFN2 ablation resulted in dilated cardiomyopathy and hypertrophy." (PMID 37175915, 2023). "In 8-week-old mice, when Mfn1 and Mfn2 were specifically and simultaneously knocked out in cardiac tissue, the cardiomyocytes showed mitochondrial fragmentation and respiratory dysfunction, rapidly developing into lethal dilated cardiomyopathy." (PMID 34660720, 2021). "Besides, Mfn2 knockout mice developed dilated cardiomyopathy." (PMID 36776252, 2023). "Cardiomyocyte‐specific deletion of both Mfn1 and Mfn2 in the adult heart resulted in mitochondrial fragmentation, impaired mitochondrial respiration, a mitochondrial UFR and a dilated cardiomyopathy." (PMID 32406208, 2020). "The systemic knockout of mitochondrial fusion proteins OPA1, MFN1, and MFN2 in mice are embryonically lethal, and the conditional combined deletion of MFN1/2 in adult cardiomyocytes triggers mitochondrial fragmentation, cardiac hypertrophy, and lethal dilated cardiomyopathy." (PMID 37175915, 2023).
dilated cardiomyopathy (continued). "Furthermore, dilated cardiomyopathy is observed in mice lacking Mfn2 at 16 weeks, and the severity increases with age." (PMID 34026850, 2021).